MALAT1 (metastasis associated lung adenocarcinoma transcript 1)
Diseases named in the same sentence as MALAT1 in open-access papers (continued):
Sharing a sentence is not in itself a finding about the gene and the disease.
diabetes (continued). "Subgroup analysis showed that sex, hypertension, hyperlipidemia, diabetes, smoking,anddrinking did not affect Malat1 expression, IL-1β, and VitD in peripheral blood ofischemic strokepatients (Table-3)." (PMID 38974129, 2023). "In addition to its role in cancer and CVD, MALAT1 is also significantly up-regulated in diabetic gastroparesis (DGP), which is a clinically relevant complication of diabetes mellitus characterized by bloating, nausea and vomiting." (PMID 31191327, 2019). "This included for example the well-known lncRNA MALAT1 and the lncRNA HYMAI, which has been studied in relation to diabetes but not previously reported in association with atherosclerosis or hypoxia." (PMID 30456215, 2018). "Since it is accepted that endothelial cells (ECs) are main targets of diabetes-induced tissue damage, recent research has also revealed novel roles for MALAT1 in diabetic complications." (PMID 29695738, 2018). "We only focused on lncRNA MALAT1 and NEAT1 considering their potential role in diabetes." (PMID 28643459, 2017). "Importantly, in a single-cell RNA sequencing (RNA-seq) dataset that contained data from ECs in kidneys from patients with diabetes with or without kidney fibrosis, we observed that MALAT1 is increased in ECs when kidney fibrosis is present." (PMID 40978530, 2025). "The upregulation of MALAT1 in diabetes in both vascular and nonvascular cells facilitates the hypermethylation of Mfn2, and this results in Mfn2 gene suppression and the inhibition of its GTPase activity, leading to the accumulation of fragmented/damaged mitochondria." (PMID 40650203, 2025). "However, MALAT1 also plays a key role in many other diseases like diabetes and neurologic disorders, which make MALAT1 not an ideal tumor biomarker." (PMID 37805491, 2023). "This study aimed to investigate transcript levels of Metastasis-associated lung adenocarcinoma transcript 1 (MALAT1), microRNA (miR)-1-3p, and C-X-C motif chemokine receptor 4 (CXCR4) in the DN patients and type 2 diabetes mellitus (T2DM) cases without neuropathy." (PMID 35368523, 2022). "However, a trend for increased lnc-MALAT1 expression was observed in diabetes mellitus patients compared to non-diabetes mellitus patients in the control group." (PMID 33111743, 2020). "Additionally, a novel signaling nexus involving MALAT1 and SAA3 has been identified which turns on inflammatory mediators in the endothelium in response to glucose level suggesting a role for MALAT1 in micro- and macro-vascular complications of diabetes." (PMID 32503170, 2020). "In addition, there was a trend for an increased proportion of diabetes (without statistical significance) in AIS patients with lnc-MALAT1 high expression." (PMID 33111743, 2020). "Diabetes results in a marked increase in the expression of ICAM-1, VEGF, and TNF-α, whereas MALAT1 knockdown could significantly reduce the induction of VEGF, TNF-α, and ICAM-1, suggesting that MALAT1 knockdown could alleviate retinal inflammation in diabetic rats." (PMID 25356875, 2014). "We have demonstrated the upregulation of MALAT1 in PBMCs of patientswith < 5 years of diagnosis compared to individuals without DM and long-termdiabetes group." (PMID 41123190, 2025). "However, it has not been reported whether lncRNA MALAT1 may participate in the pathogenesis of lower limb atherosclerosis in diabetes through NLRP3-mediated pyroptosis." (PMID 38439031, 2024). "Hence, nether depletion of miR-205-5p nor MALAT1 expression in grafted MSCs reverse diabetes." (PMID 31866580, 2019).
cervical carcinoma (96 papers, 2012 to 2025). A carcinoma arising from either the exocervical squamous epithelium or the endocervical glandular epithelium. "Overall, these findings deepen our understanding of the molecular changes linked to high‐risk HPV infections and identify PI3K, MALAT1 and H19 as promising biomarkers and therapeutic targets for cervical cancer." (PMID 41261348, 2025). "Our study devoted to research the effect that long noncoding RNA Metastasis-associated lung adenocarcinoma transcript 1 (lncRNA MALAT1) influence on cervical cancer (CC)." (PMID 36793374, 2023). "E7 targets the promoter of the lncRNA metastasis-associated lung adenocarcinoma transcript 1 (MALAT1), a lncRNA that has been associated with cervical cancer progression." (PMID 37509353, 2023). "High-risk HPV16 was reported to regulate MALAT1 expression in cervical cancer cells, whereby MALAT1 overexpression was dependent on the expression of the HPV16 E7 oncoprotein." (PMID 36458289, 2022). "Metastasis-associated lung adenocarcinoma transcript 1 (MALAT1) is a well-known lncRNA, which is strikingly up regulated in liver cancer and cervical cancer and acts vital roles in the development of human cancers and chemoresistance." (PMID 33005106, 2020). "Thus, in our present study, we aimed to investigate the underlying mechanism of MALAT1 in the progression of cervical carcinoma, which is characterized as good conservation." (PMID 34221014, 2021). "In high risk HPV-positive cervical cancer knockdown of MALAT1 also enhanced IR-induced apoptosis." (PMID 32585857, 2020). "The MALAT1 is over expressed in cervical cancer cell lines and cancer tissues infected with high risk HPVs, acts as a sponge for several miRNAs, including miR-124, miR-145, and miR-206, and favors cervical cancer progression." (PMID 32154165, 2020). "Furthermore, miR-375 overexpression can suppress EMT in cervical cancer cells by downregulating metastases-associated lung adenocarcinoma transcript 1 (MALAT1)." (PMID 30563114, 2018). "Moreover, MALAT1 deregulated expression in cervical cancer has been link with high‐risk genotypes HPV infection." (PMID 28767188, 2017). "MALAT1 could modulate GRB2 expression via competing miR-124 to promote high-risk human papillomavirus (HR-HPV)-positive cervical cancer cell growth and invasion." (PMID 28439401, 2017). "Moreover, previous study showed that the rs3200401C allele of the MALAT1 polymorphism could be a protective factor for cervical cancer development." (PMID 38517388, 2024). "Notably, the lncRNAs NEAT1 and MALAT1 have been shown to modulate radioresistance via sequestration of related miRNAs in nasopharyngeal carcinoma as well as high-risk human papillomavirus-positive cervical cancer." (PMID 28487500, 2017). "Specifically, oncogenic lncRNAs, such as HOTAIR and MALAT1, are significantly upregulated in EVs from cervical cancer patients, while the tumor-suppressive lncRNA MEG3 is significantly downregulated." (PMID 40809518, 2025). "MALAT1 (Metastasis-Associated Lung Adenocarcinoma Transcript 1), widely studied in other tumor types, promotes immune evasion and EMT in cervical cancer through EZH2 binding." (PMID 41155343, 2025). "In several types of cancers MALAT1 has been shown to be a potential biomarker including cervical cancer, uterine endometrial stromal sarcoma." (PMID 39912983, 2025). "It has been found that metastasis-associated lung adenocarcinoma transcript 1 (MALAT1) is widely upregulated in several tumors, including esophageal, liver, lung, and cervical carcinoma." (PMID 40150019, 2025).
cervical carcinoma (continued). "MALAT1, is typically downregulated in cervical cancer and impacts cell viability, cell migration and invasion, via modulating miRNA." (PMID 39912983, 2025). "MALAT1 siRNA has been shown to reduce colony formation as well as increase apoptosis in cervical cancer cell lines (CaSki and Hela)." (PMID 39912983, 2025). "siRNA/shRNA-mediated silencing of the lncRNA MALAT1 results in tumour progression, cell motility, and viability along with apoptosis in adenocarcinoma, cervical cancer." (PMID 39912983, 2025). "Metformin has also been shown to have anti-cancer effect on cervical cancer cells both in vitro and in animal models by acting on the MALAT1/miR-142-3p sponge action." (PMID 39912983, 2025). "lncRNAs that have been investigated as potential biomarkers for cervical cancer include HOTAIR MALAT1, HIF1A-AS2, PRNCR1 and UCA1." (PMID 39912983, 2025). "The expression levels of miR-124 and MALAT-1 were shown to be negatively correlated in cervical carcinoma cells, cervical patient tissues, and mice." (PMID 38511067, 2024). "It was discovered that MALAT-1 functions as an inhibitory sponge, reducing the expression of miR-124 in cervical carcinoma cells." (PMID 38511067, 2024). "For example, MALAT1 promotes resistance to cisplatin in cervical cancer by inhibiting apoptosis through activation of the PI3K/Akt pathway." (PMID 39401197, 2024). "In CC, lncRNA MALAT1 attenuates cisplatin-induced apoptosis of cervical cancer cells by regulating the STAT3 signal through miR-21." (PMID 36793374, 2023). "Metastasis-associated lung adenocarcinoma transcript 1 (MALAT1), a well-documented long non-coding RNA (lncRNA), has been previously reported to exert roles in HPV-positive cervical cancer; however, the detailed underlying mechanism has yet to be investigated." (PMID 37639643, 2023). "The positive feedback loop of exosomal MALAT1/miR-370-3p/STAT3 mediates the cisplatin resistance of cervical cancer cells affecting PI3K/Akt pathway." (PMID 36793374, 2023). "Metformin decreases migration and invasion of cervical cancer cells by suppressing MALAT1 and disrupting of MALAT1/miR-142-3p sponge." (PMID 36849958, 2023). "When endogenous MALAT1 is knocked out, it reduces the proliferation and invasion of cervical cancer cells and promotes apoptosis." (PMID 35103065, 2022). "Inhibitory direct binding of MALAT1 and miR-124 has also been shown for cervical cancer in experiments on cell cultures and in vivo." (PMID 36362406, 2022). "MALAT1 is identified as an essential regulatory factor involved in the occurrence of cervical cancer." (PMID 35103065, 2022). "LncRNA MALAT1 facilitated cisplatin resistance via modulating the PI3K/AKT pathway in cervical cancer." (PMID 36438563, 2022). "These two studies provide evidence that the function of MALAT1 in cervical cancer is related to the cell cycle." (PMID 36685972, 2022). "In CaSki (HPV 16+) cervical cancer cells, MALAT1 encourages cell proliferation, migration, and cell cycle progression." (PMID 36144454, 2022). "LncRNA ZEB1-AS1, SPRY4-IT1, MALAT1 and TUG1 are high-expression in cervical cancer cells and associated with poor prognosis." (PMID 36685972, 2022). "MiR-124, a tumor suppressor, is reportedly low in cervical cancer due to being sponged up by MALAT1." (PMID 36144454, 2022). "In agreement, the expression levels of the extracellular protein periostin and MALAT1 were found to be negativity correlated with the expression of miR-202-3p in cervix carcinoma tissues." (PMID 35682549, 2022). "Another study also found that MALAT1 can promote invasion of cervical cancer cells through sponging miR-202-3p and upregulating expression of periostin." (PMID 33777808, 2021).
cervical carcinoma (continued). "It has been shown also that knocking down MALAT1 in CaSki cervical cancer cells increased proliferation and invasion rates through BAX up‐regulation." (PMID 33094859, 2021). "In vivo assays, overexpression of miR-124, or knockdown of MALAT1 exhibited beneficial effects on tumor weight, size, and volume, together with elevating the survival rate, tightly related with the progression of cervical cancer." (PMID 34221014, 2021). "Recent study showed that MALAT1 can sponge miR-429 to promote cervical cancer metastasis and progression both in vitro and in vivo." (PMID 33777808, 2021). "LncRNA MALAT1 was found to be altered in human cervical cancer tissues, suggesting an important role in tumorigenesis." (PMID 34659524, 2021). "In this study, we found that LncRNA MALAT1 accelerates tumor growth during cervical carcinoma via inhibiting miR-124." (PMID 34221014, 2021). "Taken together, LncRNA MALAT1/miR-124 is a key axis in cervical carcinoma, exerting regulatory effects on the proliferation of the cervical tumor cell." (PMID 34221014, 2021). "Taking together the gain- and loss-of-function results, we concluded that miR-124 was the downstream of LncRNA MALAT1 in cervical carcinoma cells." (PMID 34221014, 2021). "In order to delineate the function of LncRNA MALAT1 in cervical carcinoma, we further gain insight into the effect on cervical tumor cell proliferation, which is the key activity during tumor growth." (PMID 34221014, 2021). "In cervical cancer, study showed that MALAT1 promotes invasion and metastasis of cervical cancer cells via inducing EMT." (PMID 33777808, 2021). "LncRNA MALAT1 overexpression blocked the elevation of survival rate in the miR-124-transfected group, aggravating cervical carcinoma." (PMID 34221014, 2021). "In conclusion, LncRNA MALAT1 disabled the effects of miR-124 as an inhibitory sponge, accelerating the progression of cervical carcinoma." (PMID 34221014, 2021). "We previously showed that metformin disrupts the sponge effect of long non-coding RNA MALAT1/miR-142-3p to inhibit cervical cancer cell proliferation." (PMID 32631421, 2020). "Accordingly, down regulation of MALAT1 in cervical cancer cell lines and in cervical cancer tissues reduces invasion and metastasis through the inhibition of epidermal mesenchymal transition and modulation of the MALAT1-miR-124-RBG2 axis." (PMID 32154165, 2020). "The sponging of miR-145 by MALAT1 has suggested to be involved in the mechanisms of radio-resistance in cervical cancer radiotherapy." (PMID 32154165, 2020). "The knockdown of MALAT1 inhibits cervical cancer cell invasion, which occurs by blocking EMT in both in vitro and in vivo model systems." (PMID 33291485, 2020). "The upregulation of MALAT1 promotes cancer cell growth and invasion, disables apoptotic pathways and correlates with a poor prognosis in cervical cancer patients." (PMID 33291485, 2020). "STAT3-binding sequence in the enhancer region of lncRNA MALAT1 was demonstrated to be crucial for the IL-6- or STAT3-induced MALAT1 promoter activation in cervical cancer HeLa cells." (PMID 33274204, 2020). "LncRNA MALAT1 promotes the proliferation of CasSki cervical cancer cells by diminishing expression of the cell-cycle regulatory proteins cyclin D1, cyclin E, and CDK6." (PMID 32607313, 2020). "High levels of MALAT1 characterized radioresistant cases of cervical cancer, and IR induced MALAT1 expression in cervical cancer cell lines." (PMID 32585857, 2020). "For example, metformin can disrupt the interaction between lncRNA MALAT1 and miR-142-3p to inhibit human cervical cancer cell growth." (PMID 30853913, 2019). "MALAT1 is a long non-coding RNA (lncRNA) upregulated in cervical cancer whose knockdown significantly reduces cell growth rate and invasion and increased cell apoptosis and the expression of miR-124." (PMID 30563114, 2018).
cervical carcinoma (continued). "It was illustrated that down-regulation of MALAT1 significantly increased G1 phase and decreased S phase in cervical cancer, and resulted in cell apoptosis increased obviously." (PMID 30285605, 2018). "MALAT1 is overexpressed in the cervical cancer CaSki cell line and subsequently promotes growth and invasion as well as decreasing apoptosis." (PMID 28637507, 2017). "Metastasis associated lung adenocarcinoma transcript 1 (MALAT1) has been shown to promote cell invasion and metastasis by inducting EMT in cervical cancer." (PMID 27966450, 2017). "The authors demonstrated that there was a reciprocal repression between MALAT1 and miR-145, which regulated the molecular mechanisms of radio-resistance of cervical cancer." (PMID 29147648, 2017). "MALAT1 for example is upregulated in many malignancies, and at least in ovarian cancer and cervical cancer MALAT1 promotes cell migration and invasion." (PMID 28637507, 2017). "MALAT1 also modulates radiosensitivity of HR-HPV+ cervical cancer though competitively binding miR-145." (PMID 27564100, 2016). "In cervical cancers, depletion of MALAT1 induces the expression of pro-apoptotic genes and inhibits the activity anti-apoptotic genes." (PMID 27250026, 2016). "Inhibition of MALAT1 by ASO attenuates various malignant phenotypes in cancer cells via cycle arrest in cervical cancer cells." (PMID 26448935, 2015). "Several studies have reported that MALAT1 has a critical role in cancer development, including in lung, liver, breast and cervical cancer." (PMID 24932303, 2014). "In the present study, it was identified that MALAT1 expression was upregulated in cervical cancer cell lines compared with normal cervical squamous cell samples." (PMID 24932303, 2014). "The function of MALAT1 in cervical cancer was initially studied in our laboratory; however, the molecular mechanism in cell growth and the factors inducing MALAT1 upregulation were unclear." (PMID 24932303, 2014). "In the present study, the expression of MALAT1 was detected in cervical cancer cell lines (HeLa, CaSki, SiHa and HCC94) and immortal human keratinocytes (HaCaT cells) using RT-PCR." (PMID 24932303, 2014). "Malat1 silencing significantly enhances the radio sensitivity in malignancies like nasopharyngeal, lung and cervical cancer modulating miRNA and pathways affecting DNA repair, cell cycle, apoptosis, stemness and TME reprogramming towards immunosuppression (See 79 for a review)." (PMID 40520013, 2025). "The enigmatic MALAT1 dysregulation within HPV-related cervical carcinogenesis merits in-depth investigation, offering a potential avenue for identifying therapeutic targets tailored to HPV-associated cervical cancer." (PMID 37812599, 2023). "lncRNA MALAT1 promotes cervical cancer through sponging miR-429." (PMID 36879084, 2023). "Taken together, the data suggested that downregulating MALAT1 in HPV-positive cervical cancer could suppress tumorigenesis." (PMID 37639643, 2023). "The present study aimed to investigate the role of MALAT1 in HPV-positive cervical cancer cells." (PMID 37639643, 2023). "In the present study, high expression levels of MALAT1 in HPV-Positive Cervical Cancer cells were confirmed, and silencing MALAT1 resulted in decreased rates of cell proliferation, migration, and invasion, both in vitro and in a zebrafish xenograft tumor model." (PMID 37639643, 2023). "MALAT1 expression in tissues and secretions (e.g., cervical vaginal lavage) is highly variable and has potential use as a biomarker of cervical cancer, which could be used for clinical diagnosis and treatment." (PMID 36419933, 2022). "Until now, no study reveals the associations between lncRNA MALAT1 polymorphisms and cervical cancer (CC)." (PMID 35517413, 2022).